PCDHB7 (protocadherin beta 7)
Description:
Potential calcium-dependent cell-adhesion protein. May be involved in the establishment and maintenance of specific neuronal connections in the brain.
Synonyms: PCDH-BETA7
Tractability: Antibody: UniProt places it where antibodies can reach, with medium confidence; UniProt predicts a signal peptide or a membrane-spanning region; its Gene Ontology location is reachable by antibodies, with medium confidence. PROTAC: ubiquitination databases record sites on it.
Gene: Protein-coding gene on chromosome 5 (141,172,644 to 141,176,383, forward strand). Ensembl gene ENSG00000113212.
Subcellular location: Cell membrane
Gene Ontology:
Molecular function: cell adhesion molecule binding; calcium ion binding
Biological process: cell adhesion; homophilic cell-cell adhesion; nervous system development
Cellular component: plasma membrane; membrane
Genetic constraint (gnomAD): Loss-of-function variants: 0 observed, 0.38 expected, observed/expected ratio (o/e) 0, 90% interval 0 to 1.85. That is too few expected variants to judge how well the gene tolerates losing a copy. Missense variants: 1,148 observed, 1,006.3 expected, observed/expected ratio (o/e) 1.14, 90% interval 1.09 to 1.2. Synonymous variants: 542 observed, 439.51 expected, observed/expected ratio (o/e) 1.23, 90% interval 1.15 to 1.32.
Homologues: Orthologues: macaque PCDHB7 (94% identical), rat Pcdhb20 (78% identical), mouse Pcdhb15 (78% identical), guinea pig PCDHB7 (75% identical), pig PCDHB7 (75% identical), dog PCDHB7 (67% identical). Paralogues in human: PCDHB2 (77% identical), PCDHB10 (76% identical), PCDHB9 (76% identical), PCDHB14 (76% identical), PCDHB12 (75% identical), PCDHB3 (75% identical), PCDHB15 (75% identical), PCDHB4 (74% identical), PCDHB5 (73% identical), PCDHB11 (73% identical), PCDHB13 (73% identical), PCDHB16 (73% identical), and 49 more.
Diseases named in the same sentence as PCDHB7 in open-access papers:
PCDHB7 is named in the same sentence as 3 diseases in open-access papers, as found by Europe PMC text mining. Sharing a sentence is not in itself a finding about the gene and the disease. The quoted sentences say what the papers report.
colorectal cancer (2 papers, 2022 to 2023). A primary or metastatic malignant neoplasm that affects the colon or rectum. "A functional role for the hypermethylation and gene silencing of PCDHαβγ family genes (PCDHAC2, PCDHB7, PCDHB15, PCDHGA1 and PCDHGA6) was also identified recently in colorectal cancer influencing the WNT/B-catenin pathway implicated in proliferation, survival and migration." (PMID 36443814, 2022).
PCDHB7 also shares sentences with these, for which no sentence is quoted: metastatic tumor (1 paper); prostate adenocarcinoma (1).